NLGN4Y (neuroligin 4 Y-linked)
Description:
Cell surface protein involved in cell-cell-interactions via its interactions with neurexin family members.
Synonyms: KIAA0951; HNL4Y
Tractability: Small molecule: it belongs to a druggable protein family. Antibody: its Gene Ontology location is reachable by antibodies, with high confidence; UniProt places it where antibodies can reach, with medium confidence; UniProt predicts a signal peptide or a membrane-spanning region. PROTAC: ubiquitination databases record sites on it.
Gene: Protein-coding gene on chromosome Y (14,522,573 to 14,845,654, forward strand). Ensembl gene ENSG00000165246.
Subcellular location: Cell membrane; Postsynaptic density membrane; Cell projection, dendritic spine; Cell projection, dendrite; Synapse
Pathways (Reactome):
Neuronal System: Neurexins and neuroligins
Gene Ontology:
Molecular function: protein binding; scaffold protein binding; cell adhesion mediator activity; cell adhesion molecule binding; neurexin family protein binding
Biological process: learning; social behavior; vocalization behavior; neuron cell-cell adhesion; presynapse assembly; synapse assembly
Cellular component: asymmetric, glutamatergic, excitatory synapse; dendrite; membrane; plasma membrane; postsynaptic density membrane; postsynaptic specialization membrane; symmetric, GABA-ergic, inhibitory synapse; synapse; dendritic spine; neuron to neuron synapse
Homologues: Orthologues: chimpanzee NLGN4Y (98% identical), macaque NLGN4Y (97% identical), dog NLGN4X (96% identical), tropical clawed frog nlgn4x (89% identical), zebrafish nlgn4xa (81% identical), zebrafish nlgn4xb (74% identical), mouse Nlgn4l (46% identical), Caenorhabditis elegans ace-4 (19% identical), Drosophila melanogaster Jhe (19% identical), Caenorhabditis elegans ace-3 (18% identical), Drosophila melanogaster CG3841 (18% identical), Drosophila melanogaster CG4382 (18% identical), and 37 more. Paralogues in human: NLGN4X (95% identical), NLGN3 (71% identical), NLGN1 (70% identical), NLGN2 (62% identical), CES1 (23% identical), CES4A (23% identical), CES5A (23% identical), CES2 (22% identical), ACHE (22% identical), BCHE (22% identical), CES3 (21% identical), CEL (21% identical), and 1 more.
Diseases named in the same sentence as NLGN4Y in open-access papers:
NLGN4Y is named in the same sentence as 16 diseases in open-access papers, as found by Europe PMC text mining. Sharing a sentence is not in itself a finding about the gene and the disease. The quoted sentences say what the papers report.
autism (6 papers, 2019 to 2023). Persistent deficits in social interaction and communication and interaction as well as a markedly restricted repertoire of activity and interest as well as repetitive patterns of behavior. "Interestingly, Y-chromosome harbors another autism-related gene, NLGN4Y, which encodes a trans-synaptic cell adhesion molecule that stabilizes excitatory and inhibitory synaptic activity." (PMID 32760337, 2020). "NLGN4X and NLGN4Y, as marker molecules of human autism, are considered to play an important role in the etiology of autism, the formation of synapses, and the transmission of information." (PMID 35847642, 2022).
prostate carcinoma (4 papers, 2016 to 2023). A carcinoma that arises from epithelial cells of the prostate gland. "Among these SVs, one affected NLGN4Y (neuroligin 4, Y-linked) specifically in HepG2-2.2.15, which is a tumor suppressor in prostate cancer and may contribute to the male dominance of HCC incidence." (PMID 37063858, 2023). "In addition, NLGN4Y has been suggested to be associated with male homosexuality and prostate cancer." (PMID 34215292, 2021). "Our results suggest that NLGN4Y is an important negative regulator in prostate cancer progression." (PMID 27626693, 2016). "We further showed that key regulators for biological processes myogenesis and epithelial-mesenchymal transition regulated a common set of downstream genes and identified NLGN4Y, a gene highly expressed in neurons, as a novel regulator of biochemical recurrence of prostate cancer." (PMID 27626693, 2016). "In addition, we also found that the expression of several neurotropic factors was regulated by NLGN4Y, the impact of which on these prostate cancer cells is unknown." (PMID 27626693, 2016).
atherosclerosis (1 paper, 2023). A disease characterized by the build-up of fatty material and calcium deposition in the arterial wall resulting in partial or complete occlusion of the arterial lumen. "The present study identifies genes already classified in the atherosclerosis process as genes that codify for encoding cellular adhesion molecules (NLGN4Y), cellular exocytosis (TXLNGY), induction of IFN-α (DDX3Y), cellular apoptosis (EF1AY), and prevention of protein degradation (USP9Y)." (PMID 36831031, 2023).
autism spectrum disorder (1 paper, 2022). A spectrum of developmental disorders that includes autism, and Asperger syndrome. "Its clinical association with autism spectrum disorders (ASD) is well established, however, its diversification into sex chromosome-specific copies, NLGN4X and NLGN4Y, remains uncharted territory." (PMID 35431802, 2022).
lung adenocarcinoma (1 paper, 2021). A carcinoma that arises from the lung and is characterized by the presence of malignant glandular epithelial cells. "NLGN4Y, a type I membrane protein that belonging to the family of neuroligins, was highly expressed in lung adenocarcinoma patients with poor survival." (PMID 34566519, 2021).
lung carcinoma (1 paper, 2022). "As for the genomics level, variants in NLGN4Y can regulate cell proliferation in multiple pathogenesis, though not directly reported in lung cancer." (PMID 35155435, 2022). "For the two remaining genes, NLGN4Y (ENSP00000342535) and TBR1 (ENSP00000374205), in 2019, researchers from University of Southampton summarized NLGN4Y as a multi-omics level driver for lung cancer at least at epigenomics and transcriptomics levels." (PMID 35155435, 2022).
tumor (2 papers, 2016 to 2023). "In addition to its role in controlling cell growth and motility, loss of NLGN4Y expression in cancer cells may lead to a more inflammatory tumor microenvironment." (PMID 27626693, 2016). "Thus, it remains an interesting question whether NLGN4Y loss has any effect on the surrounding nerves in PCa and how this interaction will impact tumor progression in vivo." (PMID 27626693, 2016).
cancer (1 paper, 2016). A tumor composed of atypical neoplastic, often pleomorphic cells that invade other tissues. "Since NLGN4Y is a well-known membrane protein involved in synaptic membrane adhesion, we speculated that it may also play roles in cancer cell adhesion and mobility." (PMID 27626693, 2016). "NLGN4Y is not the only neuron-derived protein that plays a role in cancer." (PMID 27626693, 2016).
NLGN4Y also shares sentences with these, for which no sentence is quoted: adenoma (1 paper); glioblastoma (1); liver cancer (1); neurological diseases (1); prostate tumor (1); prostatic intraepithelial neoplasia (1); psychiatric diseases (1); schizophrenia (1).